FBN1 (fibrillin 1)
Diseases named in the same sentence as FBN1 in open-access papers (continued):
Sharing a sentence is not in itself a finding about the gene and the disease.
tumor (continued). "In cancer, fibrillin-1 regulates TGF-β signaling, a key pathway in tumor progression and metastasis." (PMID 39273393, 2024). "In this study, genes including THBS1, CDKN1A, FBN1, TGFB1, and IGFBP3 were found to be downregulated in tumor cell lines." (PMID 35340229, 2022). "In agreement, a recent study identified a four gene antitumor signature related to the tumor microenvironment, which included RIPOR2, CCL22, PAMR1, and FBN1 genes." (PMID 36497200, 2022). "The abnormal accumulation of succinylated FBN1 leads to the upregulation of extracellular factors, such as MMP2, and promotes various responses, such as the intracellular proliferation signals of tumor cells." (PMID 35901491, 2022). "We found that the supernatant was rich in FBN1, and the intracellular PI3K/Akt signaling pathway was continuously activated in tumor cells." (PMID 35901491, 2022). "The expression of FBN1, RARRES1, and TIMP3 was positively correlated with multiple tumor-related pathways." (PMID 36424614, 2022). "In summary, cross‐talk between tumor cells and CAFs increased succinylated FBN1 and MMP2 expression and promoted tumor cell invasion into the stroma." (PMID 35901491, 2022). "FBN1, HIC1, and SFRP4 were lower in the tumor than normal tissues; the expressions of other ERGs were the opposite." (PMID 35095892, 2021). "The results revealed that the mRNA expression levels of DLX4, FBN1, HIC1, HOXB9, ONECUT2, and SIX1 were significantly different between tumor samples and normal tissues, which were consistent with the results from TCGA." (PMID 35095892, 2021). "We found ACAP1, IFIT3 and TAP1 were upregulated in tumor samples, while ADAMTS9, COL6A2, FBN1 and FSTL1 were downregulated in tumor specimens." (PMID 34112144, 2021). "Compared with the mice injected with RL95-2-NC cells, those injected with RL95-2-shFBXO2 cells displayed an attenuated rate of tumor growth while knockdown of both FBXO2 and FBN1 rescued this phenotype." (PMID 32984335, 2020). "With regards to the clinical analysis of ccRCC samples from microarrays of GSE66272 and GSE73731, the upregulation of L1CAM and FBN1 and downregulation of AUTS2, MAPT, AGT and USH1C were observed along with an increase in tumor grade." (PMID 29215599, 2017). "In addition, previous studies have reported that FBN1 and SFRP4 act as tumor suppressor genes, supporting our results." (PMID 41020879, 2025). "This accumulated FBN1 then interacts with the integrins β3 and β5, triggering the release of TGFβ1 and the activation of the PI3K/Akt pathway, which ultimately facilitates cell proliferation and tumour progression." (PMID 38213532, 2023). "Identifying the modification site and using it as a therapeutic target allows us to interfere with tumor rather than normal tissues as specifically as possible by intervening with the succinylation‐specific modification of FBN1." (PMID 35901491, 2022). "FBN1, FN1, HGF, MMP9, THBS1, and VCAN may be new GC prognostic targets by affecting tumor purity, TMB, TME score, and multiple oncogenic signaling pathways." (PMID 33014013, 2020). "However, tumor weights were much higher with double-knockdown of FBXO2 and FBN1 compared with the RL95-2-shFBXO2 group." (PMID 32984335, 2020). "We found that the expression levels of two upregulated genes (L1CAM and FBN1) were also increased along with tumor grade and that the expression levels of four downregulated genes (AUTS2, MAPT, AGT and USH1C) were decreased along with tumor grade." (PMID 29215599, 2017). "FBN-1 expression was evaluated in the tumour tissue, in GCNIS and in adjacent non-neoplastic testicular tissue in all available cases." (PMID 27487789, 2016). "FBN1 is highly expressed in this cluster, indicating activity in an extracellular matrix organization and EMT process; CAF in metastatic microenvironment highly expresses CCL5 which promotes the migration of tumor cells; while high expression of tumor-suppressive genes such asTFF1 was also detected." (PMID 36148946, 2022).
tumor (continued). "Lack of the FBN1 protein, then, may play a potential role in tumors and the FBN1 gene may be considered an essential tumor-suppressor gene." (PMID 32984335, 2020). "It is possible that the dependency of FBN-1 and LTBP-4 on FN is primarily required in the early postnatal phase when blood vessels still undergo intensive remodeling and growth, or, alternatively, it is possible that this dependency is tissue specific (aorta versus tumor)." (PMID 30036393, 2018). "In tumor samples gene expression analysis showed no significant variation between WT and heterozygous KIT mutated tumors, with a high inner variability in ANXA8, FBN1, GALNTL4, MFAP5 and RABEP1 expression, which was partly reduced by separating exon 9 and exon 11 mutated tumors." (PMID 23593401, 2013). "And transcriptional data reveal that compared to the adjacent non-tumorous samples, expression of COL3A1, COL1A2, FBN1, IGFBP7, and FSTL1 was significantly elevated in the tumor tissue." (PMID 38478111, 2024).
cancer (43 papers, 2011 to 2025). A tumor composed of atypical neoplastic, often pleomorphic cells that invade other tissues. "In this context, dysregulation of FBN1 expression has been associated with the pathogenesis of various human diseases including cancer, cardiovascular and kidney disorders." (PMID 38269088, 2023). "Among them, Cspg5, Fbn1, Thbs1, Pdpn, Etv4, Unc5a, Ntn1, and Nat8l were associated with the OC prognosis; Cspg5, Fbn1, Pdpn, and Unc5a were correlated with patient age; Fbn1, Mycn, Nat8l, Unc5a, and Ntn1 were significantly correlated with individual cancer stage." (PMID 36829196, 2023). "It is therefore evident that succinylation of both LDHA and FBN1 is favorable for cancer development." (PMID 40867281, 2025). "The extracellular matrix (ECM) is essential for tumorigenesis as well as cancer progression, and extracellular matrix protein fibrilin-1 (FBN1) is a major component of the ECM." (PMID 40867281, 2025). "Dysregulation of FBN1 is involved in the pathogenesis of many human diseases, such as cancers, cardiovascular disorders and kidney diseases." (PMID 38269088, 2023). "FBN1 is often found to be dysregulated in several human diseases such as cancer, cardiovascular and kidney diseases." (PMID 38269088, 2023). "We scored and compared normal and cancer tissues, and found that the overall survival (OS) was shorter for patients with a high level of succinylated FBN1 than those with a low level." (PMID 35901491, 2022). "This is consistent with other EMT pathway genes in the skin; COMP, CTHRC1, ECM2, FBN1, LOX, and SPARC were all upregulated in samples with a mutation in a cancer gene." (PMID 36531005, 2022). "Lower FBN1 expression, however, was noted in cancers that originate from fibrous tissues, including gynaecological cancers, such as cervical (CESC), endometrial (UCEC), uterine (UCS) and ovarian (OV) cancers." (PMID 34386072, 2021). "The presented data from GEPIA in this study, show differential FBN1 expression in 14 cancers, with higher expression noted in cancers of the stomach (STAD) and pancreas (PAAD)." (PMID 34386072, 2021). "Of the presented cancers, the female reproductive tissues: uterine, cervical, and ovarian exhibit lower FBN1 expression compared to corresponding normal tissues." (PMID 34386072, 2021). "We expanded our observations by assessing the expression of FBN1 across 33 different cancer types using TCGA datasets through GEPIA." (PMID 34386072, 2021). "ADAMTSL6 interacts directly with fibrillin-1 and promotes early-stage fibrillin-1-microfibril assembly, and indirectly regulates the TGFβ signaling pathway in the cancer context." (PMID 34912367, 2021). "Due to similarities between ESCs and GCNIS, we suppose, that FBN-1 is involved in similar processes in GCNIS as in ESCs and based on our results we suggest, that GCNIS cells start to produce FBN-1 in order to ensure growth and self-renewal of cancer cells." (PMID 27487789, 2016). "Most deregulated genes have been reported as potentially implicated in cancer and severals, as ANXA8 and FBN1, are highlighted by both, mRNA and miRNA analyses." (PMID 23593401, 2013). "While the importance of the microenvironment is appreciated in development and cancer, this is to our knowledge the first evidence for microenvironmental regulation by fibrillin-1." (PMID 22242013, 2012). "The level of mRNA expression of CNRIP1, FBN1, INA, and SNCA was strongly associated with promoter methylation status in cancer cell lines (P = 0.037, P = 0.017, P = 0.006, and P = 0.001, respectively)." (PMID 21777459, 2011). "FBN1 is expressed at higher levels in the cancer stroma than in normal ovarian stroma." (PMID 41008788, 2025). "The decreased levels of FBN1, encoding fibrillin 1, an ECM glycoprotein that is a structural component of calcium-binding microfibrils, could lead to the inhibition of cancer cell invasion." (PMID 37834191, 2023).
cancer (continued). "Similarly, the K672 and K799 sites of FBN1 were found to be hypersuccinylated in cancer cells, which prevents its binding to MMP2." (PMID 38144777, 2023). "In addition, FBN1 also plays an important role in the Wnt/β-catenin signaling pathway that regulates cancer cell migration." (PMID 36639776, 2023). "As such, this might also explain, at least in part, the varying expression of FBN1 among different cancer types." (PMID 34386072, 2021). "The downregulation of FBN1 in this cohort of cancers may be suggestive of tissue-specific expression compared to up-regulation in other malignancies." (PMID 34386072, 2021). "FBN1 is the primary component of microfibrils at the extracellular matrix, which might be involved in cancer progression." (PMID 33604385, 2021). "The prognostic value of FBN1 in cancer is continually evolving." (PMID 34386072, 2021). "Among of them, SLC12A5, MYO1B, FBN1, ITGAV, KLF4 and USP28 were more reported to effect cell proliferation and migration in human cancers." (PMID 39951205, 2025). "In our study, we analyzed the Cancer Cell Line Encyclopedia (CCLE), The Cancer Genome Atlas (TCGA), and the Genomics of Drug Sensitivity in Cancer (GDSC) database, to select six genes (FBN1, FN1, HGF, MMP9, THBS1, and VCAN) as target genes." (PMID 33014013, 2020). "As integral components of microfibrils, which provide strength and elasticity to the extracellular matrix, fibrillins, particularly FBN-1 and FBN-2, are thought to be involved in cancer pathogenesis and maintenance of the pluripotency of embryonic stem cells." (PMID 29042385, 2017). "Recently, many epigenetic biomarkers have been studied in cancer diagnosis, including hMLH1, E-cadherin, CDKN2A, CDKN2B and APC in GC and SEPT9, SFRP2, THBD, SDC2, VIM and FBN1 in CRC." (PMID 29137404, 2017). "In spite of several genome-wide epigenetic studies, only a few reports include DNA methylation data and potential subsequent epigenetic silencing of CNRIP1, FBN1, INA, and SNCA in cancer." (PMID 21777459, 2011). "To identify a potential novel gene target, we looked for highly connected genes that have not been extensively studied as cancer targets and then focused on FBN1, a structural component of calcium-binding microfibrils." (PMID 36119108, 2022). "This study also identified ITGB1, FBN1, and THBS1 as putative pan-cancer detection biomarkers." (PMID 36010848, 2022). "In addition, the core genes IGFBP1, FBN1, and SERPINA1 selected in this study have also been reported to be involved in the regulation of cancer cell migration and invasion." (PMID 34692659, 2021). "With further growth and differentiation of cancer cells, the importance of FBN-1 for attachment and self-renewal probably decreases, which could lead to the decreased expression of FBN-1 in the invasive TGCTs." (PMID 27487789, 2016). "Cancer cells in GCNIS as well as in TGCTs exhibit several similarities with embryonic stem cells; therefore in this translational study we investigated expression of FBN-1 in patients with TGCTs." (PMID 27487789, 2016). "ITGB1, FBN1, and THBS1 have not been coherently identified as putative “pan-cancer” early detection biomarkers because a similar study to this one has not been conducted previously." (PMID 36010848, 2022). "However, no research has shown that KNG1, FBN1, MATN3, and SERPINC1 play an important role in cancer chemotherapy resistance." (PMID 34737677, 2021).
genetic disorder (34 papers, 2012 to 2026). "FBN1 is a structural protein that functions as a multimer and, like several collagens, has the characteristics of a protein whose mutations cause an AD genetic disease through the DN effect." (PMID 39939800, 2025). "As such, mutations in FBN1 gene cause a wide variety of genetic disorders with pleiotropic manifestations." (PMID 38269088, 2023). "While much has been learned about the connection and mechanistic interplay between FBN1 gene mutation and various genetic diseases, the role of dysregulated FBN1 in the pathogenesis of different diseases is just beginning to be unveiled." (PMID 38269088, 2023). "WMS is a genetic disorder with the autosomal dominant form caused by a mutation in the FBN1 gene." (PMID 39421111, 2024). "Human genetic diseases due to mutations in gene encoding FBN1." (PMID 38269088, 2023). "The most studied genetic disorder associated with mutations in FBN1 is MfS." (PMID 32879762, 2020). "Most genetic diseases such as MFS, SSS and SSc caused by dysregulated FBN1 exhibit an upregulated ERK1/2 signaling." (PMID 38269088, 2023). "Here, we have provided further evidence for the existence of a distinct genetic disease, MPLS, caused by FBN1 mutations." (PMID 31774634, 2020). "All together, these related genetic disorders suggest that specific ADAMTSL (at least ADAMTSL-2 and -4) and ADAMTS (ADAMTS-10 and -17) proteins modulate fibrillin-1 function in the skeleton, skin, joints, muscle, and eye." (PMID 22242013, 2012).
autosomal dominant disease (10 papers, 2016 to 2024). Autosomal dominant form of disease. "MFS is an inherited autosomal dominant disease caused by mutations in the fibrillin-1 gene (FBN1)." (PMID 38177536, 2024).
cardiovascular disease (9 papers, 2013 to 2023). "MFS research has expanded over the last 15 years because of development of MFS mouse models, however, this has not yet translated into novel treatment approaches to compensate for the FBN1 gene defect that causes cardiovascular disease." (PMID 30841577, 2019). "Overall, we identified 5 reportable variants classified as KP or EP in the DSP, MYH7, and FBN1 genes, which have been reported to cause different types of cardiovascular diseases." (PMID 30217213, 2018). "While cardiovascular disease in MFS may be caused by different FBN1 defects and modifying factors, promoting cardiovascular repair would benefit all types of MFS patients." (PMID 30841577, 2019). "Fibrillin-1 microfibrils are the scaffold for elastin deposition, forming the elastic fibers, a major component of the aortic wall.Thus, fibrillin-1 dysmorphism is considered to be the primary causal factor for the cardiovascular disease's related morbidity and mortality in MFS." (PMID 31725753, 2019). "The associations of other genetic variants on ZBED9 with QRS amplitude and interval in Europeans and also ABHD17C and FBN1 with BP traits or cardiovascular diseases in Europeans and East Asians were previously reported in GWAS literature." (PMID 34083597, 2021). "Two previously reported loci of FBN1 and ABHD17C to show evidence for a strong association with BP and cardiovascular disease traits, so they were prioritized as biological targets (overall association score = 1)." (PMID 34083597, 2021).
infection (5 papers, 2022 to 2025). The state of being infected such as from the introduction of a foreign agent such as serum, vaccine, antigenic substance or organism. "There is further evidence of fibrosis at 96 h post infection with fibrillin 1, collagen type IV, and type VI being significantly increased in abundance." (PMID 40665229, 2025). "However, FBN1 decreases the infection level of mosaic virus in tobacco." (PMID 39683095, 2024).
heart disease (3 papers, 2013 to 2025). "We further examined the molecular markers for cardiac disease and fibrosis, including NPPA, NPPB, ACTA1, and FBN1." (PMID 35369338, 2022).
kidney disease (3 papers, 2019 to 2023). "In addition to the FBN1 gene, we also found that 27 patients had mutations in the PKD1 gene, however these patients did not have kidney disease, and 16 of the 27 patients expressed aortic related complications." (PMID 33200202, 2020).
musculoskeletal disorders (3 papers, 2022 to 2024). "We observed that MYH7, RYR1, FBN1, TNNT1, MYBPC1, COL1A1, and CHRNB1 were related to musculoskeletal disorders." (PMID 38658807, 2024).
skeletal dysplasia (3 papers, 2020 to 2023). Any Mendelian diseases that affects growth and development of the skeleton. "A notable aspect of this study was the frequency of heterozygous mutations detected in genes previously associated with skeletal dysplasia (NPR2, ACAN, CASR, COMP, and FBN1), confirming the dose effect of cartilage matrix proteins in growth and development." (PMID 37605180, 2023). "Considering the skeletal dysplasia and poor efficacy of rhGH treatment in patients with FBN1 mutation, we did not treat our patient with rhGH." (PMID 37239376, 2023). "Indeed, the phenotypes of FBN1, located in 15q21.1, are related to severe short stature, skeletal dysplasia, toe walking, normal intelligence, and distinctive facial features, consistent with those of our proband." (PMID 37239376, 2023).
vasculopathies (3 papers, 2014 to 2024). "The accelerated aging phenotype is also of interest as it offers unique insight into fundamental processes underlying vascular aging with potential relevance for the Fbn1-associated patient vulnerability to vasculopathies." (PMID 38461168, 2024). "Similar to other conditions known as TGF-β vasculopathies (MFS, which is caused by FBN1 mutations and LDS, which is caused by TGFBR1, TGFBR2, SMAD3 and TGFB2 mutations), the SLC2A10 loss of function activates the TGF-β signaling pathway." (PMID 25373504, 2014).
adenocarcinoma (1 paper, 2022). A common cancer characterized by the presence of malignant glandular cells. "Three proteins, namely, ITGB1, FBN1, and THBS1, were identified as common across the examined adenocarcinomas, DCIS and BC of all grades." (PMID 36010848, 2022). "Finally, could serological detection of proteins such as ITGB1, FBN1, and THBS1 be employed as a general screening tool for adenocarcinomas ?" (PMID 36010848, 2022).
digestive system tumors (1 paper, 2021).
metabolic disorders (1 paper, 2025). "Conversely, increased FBN1 signaling has been associated with pro-inflammatory microenvironments in metabolic disease, suggesting that elevated FBN1 may exacerbate TNF-α-mediated neuroinflammation." (PMID 41399726, 2025). "Genetic and epigenetic regulation of FBN1 is altered in metabolic disorders, including GDM, suggesting a wider functional remit beyond connective tissue integrity." (PMID 41399726, 2025).